ATG7 (autophagy related 7)
Diseases named in the same sentence as ATG7 in open-access papers (continued):
Sharing a sentence is not in itself a finding about the gene and the disease.
melanoma (continued). "Next, we detected a consistent decrease in ATG7 expression from benign nevi to primary melanomas and in contrast to ATG5, the levels of ATG7 were further reduced in metastatic tissues." (PMID 34458153, 2021). "The expression levels of the autophagy proteins ATG5, ATG7, ATG16L1, and two autophagic markers, LC3B and p62, were assessed in melanoma patients by immunohistochemistry." (PMID 34458153, 2021). "To further validate that ectopic expression of HopQ induces autophagy in melanoma cells, leading to suppressed vimentin expression, we disrupted autophagy by silencing ATG5 and ATG7 with siRNA." (PMID 32286254, 2020). "SIRT6 knockdown was found to cause a marked decrease in the protein levels of LC3 II (autophagy related form of LC3), ATG3, ATG7, SQSTM1 and BECN in melanoma cells." (PMID 29234488, 2017). "Accordingly, in melanoma cells, co-treatment of THC with the autophagic flux inhibitor chloroquine or knockdown of autophagy-related 7 (Atg7), an essential molecule for induction of autophagy, resulted in suppression of THC-induced autophagy as well as cell death." (PMID 35277658, 2022). "Therefore, we decided to further investigate NRF1-mediated transcriptional regulation of ATG7 and ATG5 genes in melanoma cells." (PMID 34458153, 2021). "In addition, we determined the expression of stress (CHOP, XBP1, and BIP) and autophagy (DRAM1, P62, ATG5, and ATG7) marker genes; furthermore, we successfully developed an HA15-resistant melanoma cell line." (PMID 33498201, 2021). "Taken together, the migration of melanoma cells might be regulated by ATG5 and ATG7 independent on their role in autophagy." (PMID 34458153, 2021). "Importantly, downregulation of both ATG5 and ATG7 correlates with a less favourable outcome for patients, suggesting the potential use of ATG5 and ATG7 levels as prognostic markers in melanoma in order to recognize the more aggressive, metastatic phenotype." (PMID 34458153, 2021). "The lysosomal inhibitor Baf A1 inhibited the production of MDC-positive vesicles induced by DDA and, in line with this, KD of the autophagic proteins ATG7, VPS34, and BECN1 in melanoma cells inhibited DDA-induced LC3-II formation, DDA-induced MDC-labeled punctates, and DDA-induced cell death." (PMID 29199269, 2017). "However, TRI-03 failed to produce these effects in mice injected with Atg7-shRNA-transfected melanoma cells." (PMID 40486906, 2025). "Although autophagy loss in this case was also associated with increased DNA damage, dysfunctional mitochondria, and accumulated p62, consistent with its traditional role in preserving organelle integrity, the exact mechanisms that link ATG7 to oncogene-driven melanoma are not well-defined." (PMID 36670319, 2023). "This suggests that Atg7-deletion should not have the same impact in the context of Pten-deficiency, as PI3K pathway activation via Pten deletion is known to abrogate oncogene-induced senescence and contributes to melanoma development." (PMID 33664481, 2021). "Furthermore, in Atg7iECKO melanoma lung metastasis and subcutaneous tumor models, we did not observe significant inhibition of tumor progression or development following endothelial cell-specific Atg7 gene deletion." (PMID 39744218, 2025).
bladder cancer (32 papers, 2016 to 2025). "Previous studies have found that ATG7 not only promotes autophagy but is also associated with the progression of bladder cancer." (PMID 37269429, 2023). "A related study on bladder cancer showed that overexpression of autophagy-associated gene 7 (ATG7) impairs FOXO3a protein expression, thereby reducing the transcription of the miR-145 promoter and its overall expression through direct binding to its promoter region." (PMID 40689207, 2025). "A study (NCT03254888) on bladder cancer patients with confirmed histopathology employed quantitative real-time PCR to estimate ATG7 levels and used immunohistochemistry to determine LC3A levels as markers of autophagy." (PMID 39273093, 2024). "Previous studies have demonstrated significant impacts of ATG7 on the invasive behavior of bladder cancer cells." (PMID 39464718, 2024). "-The TET1/USP28/CD44/RhoGDIβ pathway was identified as the regulator of the oncogenic activities of ATG7 for stem-like property, invasion, and lung metastasis of human bladder cancer cells." (PMID 35269796, 2022). "Our recent study has discovered that ATG7-mediated autophagy activity is elevated in human bladder cancers, which is crucial for bladder cancer invasion and tumor growth." (PMID 36575197, 2022). "In our study, the autophagy process induced by C-2 is associated with autophagy factors such as ATG7, ATG5, ATG3, p62, LC3 and Beclin-1, therefore, the ability of C-2 to induce autophagy in bladder cancer cell lines was confirmed." (PMID 31685029, 2019). "Here, we reported that PD-L1 protein is regulated by ATG7-autophagy with an ATG7-initiated positive feedback loop in bladder cancer (BC)." (PMID 30871066, 2019). "Additionally, PD-L1 was found to form a positive feedback loop that enhances the oncogenic role of ATG7 in promoting stem cell-like properties, invasion, and tumorigenesis in human bladder cancer." (PMID 40689207, 2025). "These altered cell cycle kinetics are consistent with the increased Ki67 staining intensity observed by tumor IHC and concordant with a previous study demonstrating that ATG7 KD by siRNA in human bladder cancer cells increased the fraction of cells in S phase and G2/M phase 38." (PMID 38302465, 2024). "This suggests that Atg7 plays a role in regulating the invasion of bladder cancer cells." (PMID 37834333, 2023). "For example, the ATG7 gene, which is overexpressed in invasive bladder cancer tissue, can promote autophagic degradation of the HNRNPD (ARE/poly(U)-binding/degradation factor 1) protein, which, in turn, increases ARHGDIB mRNA stability and bladder cancer cell invasion." (PMID 36875752, 2023). "miR-154 exerts a suppressor role by directly targeting ATG7 in bladder cancer." (PMID 34691238, 2021). "The elevated UCA1 upregulated ATG7 in bladder cancers by sponging miR-582-5p." (PMID 33050642, 2020). "Finally, relevant to our initial observation that autophagy is elevated in urinary bladder and prostate cancer samples, we depleted either ATG5 or ATG7 in a human bladder carcinoma cell line T24 and in a human prostate cancer cell line PC-3." (PMID 31409894, 2020). "The hypoxic exosomes facilitated bladder cancer progression through EMT both in vivo and in vitro, which may be caused by UCA1/miR-582-5p/ATG7-mediated autophagy." (PMID 33050642, 2020). "Given that ATG7 upregulation is observed in 9 out of 11 cases from the The Cancer Genome Atlas (TCGA) bladder cancer database, we further tested the relationship between ATG7 and BC invasion in an in vitro cell culture model and tumor growth in xenograft tumor model." (PMID 31016112, 2019). "Furthermore, inhibition of autophagy with ATG7 siRNA and bafilomycin A1 also confirmed that blocking autophagy enhanced OA-induced apoptosis of bladder cancer cells." (PMID 28978086, 2017). "ATG7 overexpression stabilizes CD44 by upregulating USP28 protein, which in turn modulates stem cell-like properties, invasion and human lung metastasis in bladder cancer." (PMID 40707430, 2025).
bladder cancer (continued). "Using ATG7-targeted siRNA, CQ, and ComC to repress autophagy, and Rap and AICAR to stimulate it, we found that autophagy inhibition and induction suppressed and stimulated, respectively, BA-mediated apoptosis in bladder cancer EJ and T24 cells." (PMID 34510030, 2021). "ATG5 and ATG7 knockout mouse models would also help to understand the possible role of SCFA on autophagy, as for example, butyrate induced mTOR pathway-activated autophagy in bladder cancer cells and nasopharyngeal carcinoma cells." (PMID 32664466, 2020). "Moreover, inhibiting autophagy by siRNA to autophagy related 7 (ATG7) or with autophagy inhibitor bafilomycin A1 and 3-methyladenine (3-MA) or AMPK inhibitor dorsomorphin (compound C) promoted OA-induced deaths of bladder cancer cells." (PMID 28978086, 2017).
pancreatic cancer (31 papers, 2012 to 2025). "In pancreatic cancer, Atg5 or Atg7 deficiency resulted in increased PanIN lesions, albeit lack of progression to malignant disease." (PMID 37735513, 2023). "Our results demonstrated that TET promotes the transcription and protein expression of ATG7 in pancreatic cancer cells, suggesting that TET also regulates autophagy by promoting the formation of autophagosomes." (PMID 38987818, 2024). "We found that TET exhibited significantly enhanced cytotoxicity in pancreatic cancer cells after inhibiting ATG7 expression." (PMID 38987818, 2024). "- CircATG7 induces autophagy, motility, proliferation, and metastasis of pancreatic cancer by miR-766-5p/ATG7 and HUR/ATG7 axis." (PMID 37205191, 2023). "Autophagy related 7 (ATG7) activation inhibits autophagy, reducing pancreatic cancer cell proliferation and metastasis." (PMID 37205191, 2023). "Autophagy related 7 activation inhibits autophagy, reducing pancreatic cancer cell proliferation and metastasis." (PMID 37205191, 2023). "CircATG7 overexpression increased pancreatic cancer cell motility, proliferation, and autophagy, while ATG7 inhibition diminished its effects." (PMID 37205191, 2023). "ATG5-ATG7-NCOA4 pathway is critical for the regulation of iron metabolism and knockout of ATG7 can lead to a limited elastin-induced ferroptosis in pancreatic cancer cell lines." (PMID 35911966, 2022). "The group of Michael Karin found an increase in several EGFR ligands including EGF after mutationally activated NRF2 in a mouse model of hepatomegaly as well as in human pancreatic cancer cells with ATG7 deletion." (PMID 33916908, 2021). "The activation of the Atg5/Atg7-NCoA4 axis in pancreas cancer PANC-1 cells can degrade ferritin, inhibit the expression of the heavy chain of ferroprotein, and induce ferroptosis." (PMID 34413966, 2021). "Erastin-induced ferroptosis has been shown to be suppressed by Atg5 or Atg7 deficient mouse embryonic fibroblasts (MEFs), as well as in human pancreatic cancer and human fibrosarcoma cell lines with knockdown of Atg5 or Atg7 protein levels with shRNA." (PMID 31936109, 2020). "We further evaluated two of these candidates by paired-end RNA-seq, from which we identified novel gene fusions, ATG7/RAF1 in pancreatic cancer and BCL6/RAF1 in anaplastic astrocytoma." (PMID 23637631, 2013). "We further characterized the oncogenic relevance of ATG7/RAF1 in pancreatic cancer, using RNAi to knockdown its expression." (PMID 23637631, 2013). "Mechanistically, we found that THM mediated the post-transcriptional regulation of autophagy activation by targeting YTHDF2, thereby preventing the reading of the m6A modifications of ATG5 and ATG7 mRNAs, ultimately resulting in autophagic death in pancreatic cancer cells." (PMID 40756353, 2025). "In pancreatic cancer, an autophagy-associated circRNA circ-autophagy related 7 (circATG7, has_circ_0064288) was reported to facilitate cell autophagy, proliferation and invasion through miR-766-5p/ATG7 and HUR/ATG7 axis, thereby promoting PC progression." (PMID 38177102, 2024). "Additionally, we observed that TET promoted the expression of ATG7 protein in pancreatic cancer cells in a dose-dependent manner." (PMID 38987818, 2024). "In our previous work, we had found several metabolic changes upon biallelic deletion of Atg7 in a mouse model of pancreas cancer and we reasoned that some of these changes may also occur in Atg7+/− tumors." (PMID 35867735, 2022).
pancreatic cancer (continued). "In one study, inhibiting the expression of the autophagy-related genes autophagy-related protein 5(AGT5) and ATG7 in vitro to prevent the death of erastin-induced pancreatic cancer cell lines (PANC1 and PANC2.03) significantly reduced the ferrous iron and malondialdehyde levels in the cell." (PMID 34503532, 2021). "Furthermore, inhibition of autophagy by chloroquine or 3-methyladenine, or knockdown of Atg-7 all enhanced the cytotoxicity of gambogic acid, suggesting that gambogic acid-induced autophagy improves the survival of pancreatic cancer cells." (PMID 30627053, 2019). "Moreover, another example that injecting cancer cells into sciatic nerve of nude mice to establish a dorsal root ganglion (DRG) co-culture system with cancer cell lines, found that pancreatic cancer cells induce SCs autophagy via NGF/ATG7 pathway, thus promoting pancreatic cancer PNI." (PMID 40248695, 2025). "Despite this, it is unknown how ATG7 governs pancreatic cancer." (PMID 37205191, 2023). "We also investigated the correlation between the expression of NURR1 and ATGs (ATG7 and ATG12) in pancreatic tumor samples by performing correlation analysis." (PMID 35582016, 2021). "For example, silencing of ATG5 or ATG7 in GEM models of KRASG12D- or BRAFV600E-driven cancer significantly delayed the onset and altered the histopathology of lung or pancreatic cancer." (PMID 34298710, 2021). "To study the prognostic significance of ATG7 and ATG12 in PDA, we examined TCGA, which showed a significant increase in expression of ATG7 in pancreatic tumors (T = 179) compared with normal tissue samples (n = 171)." (PMID 35582016, 2021). "To determine the role of autophagy in pancreatic cancer stemness, we established lentivirus-mediated stable ATG5, ATG7, and BECN1 knockdown cell lines shATG5, shATG7, and shBECN1 derived from PANC-1 cells and analyzed their CSC activity." (PMID 26458814, 2015). "Studies in Kras-mutant pancreatic cancer mice have shown that the absence of autophagy genes such as ATG5 or ATG7 blocks the progression from low- to high-grade pancreatic intraepithelial neoplasia and pancreatic ductal adenocarcinoma." (PMID 38987818, 2024). "Also, after radiotherapy, HOTAIR down-expression by overexpression of Wnt inhibitory factor 1 (WIF-1) and autophagy related 7 (ATG7) reduces radio-resistance and cell proliferation and induces apoptosis in pancreatic cancer patients." (PMID 38559560, 2024). "Meanwhile, bioinformatic analysis indicated that ATG7 expression was upregulated and negative with the prognosis in the pancreatic cancer." (PMID 35288538, 2022). "The combination of an NGF inhibitor and chloroquine can prevent the occurrence and development of perineural invasion in pancreatic cancer, and potential molecular neurotrophic factors, such as NGF, secreted by cancer cells can induce autophagy of SCs by upregulating ATG7 expression." (PMID 35109895, 2022). "As Atg7 and Beclin1 are two key components for autophagosome biogenesis, we also observed a decrease in LC3 II conversion from LC3 I upon knockdown of Atg7 and Beclin1 in both the pancreatic cancer cells." (PMID 25469510, 2014). "We did not observe any significant change in Atg7 or Beclin1 expression after GIPC depletion in both pancreatic cancer cells." (PMID 25469510, 2014). "Additionally, to confirm whether THM induced autophagy in pancreatic cancer cells, we further assessed the expression levels of multiple autophagy-related proteins, including ATG5, ATG7, LAMP2, SQSTM1 and LC3B, in THM-treated cells." (PMID 40756353, 2025). "The research about pancreatic cancer stem cells found that rottlerin could reduce the viability of pancreatic cancer stem cells and induce apoptosis to form cytoplasm cavity and upregulate autophagy markers LC3-I, LC3-II, Atg7, and Beclin-1." (PMID 29234398, 2017).
pancreatic cancer (continued). "Moreover, NURR1 regulated expression of two major autophagic genes, ATG7 and ATG12, which are also overexpressed in pancreatic tumors and like NURR1 are negative prognostic factors for patient survival." (PMID 35582016, 2021).
Insulin resistance (29 papers, 2013 to 2025). Increased resistance towards insulin, that is, diminished effectiveness of insulin in reducing blood glucose levels. "Obesity suppresses essential autophagic proteins like ATG7, disrupting lipophagy, impairing organelle function, inducing lipid droplet accumulation, and causing ER stress, contributing to insulin resistance." (PMID 40420631, 2025). "Relevant to our study, within Bacteroides genus, the observed enrichment of B. acidifaciens is associated with lower body weight, fat mass and improvement of insulin resistance in hepatic autophagy-related gene 7 (Atg7)-deficient mice." (PMID 30291258, 2018). "shRNA‐induced loss of ATG7 results in insulin resistance in C57BL/6 mice and reduced glucose clearance, but it was not reported whether fasting glucose levels were also repressed." (PMID 40420631, 2025). "Both impaired autophagy and inhibition of ATG7 can induce disruption of the insulin pathway and insulin tolerance, meaning that decreased autophagy activity can lead to insulin resistance." (PMID 41150819, 2025). "In this regard, it has been demonstrated that in obese mice, global ATG7 haplodeficiency leads to insulin resistance as well as the maturation of pro-IL-1β to IL-1β and increased inflammation." (PMID 37876013, 2023). "Suppression of autophagy-related gene 7 (ATG7) impairs insulin signaling, whereas restoration of ATG7 expression improves insulin resistance." (PMID 36499655, 2022). "Despite this perturbation in skeletal muscle mass, glucose tolerance is enhanced in chow-fed, skeletal muscle-specific Atg7 knockout mice, and these mice were protected from diet-induced insulin resistance." (PMID 34336862, 2021). "To further elucidate the vital role of autophagy in the therapeutic effect of KD on insulin resistance, we down-regulated the autophagy gene Atg7 in hepatocytes using small interfering RNA (siRNA)." (PMID 34122092, 2021). "Consistently, our data demonstrated that the inhibition of autophagy by ATG7 siRNA and 3-MA ameliorated the insulin resistance in PA-treated HK-2 cells." (PMID 29311680, 2018). "When ATG7 is repressed in livers of lean mice, they develop severe insulin resistance, which also suggests a role for autophagy in insulin action." (PMID 28768896, 2017). "Consistently, adenoviral-mediated depletion of ATG7 in the livers of lean mice leads to insulin resistance, which correlates with ER stress, effects that are significantly improved when ATG7 is reexpressed in hepatocytes." (PMID 28913352, 2017). "A previous study showed that suppression of hepatic gene ATG7 in mice results in increased ER stress and insulin resistance." (PMID 25786112, 2015). "Deficient autophagy by suppression of autophagy related gene 7 (ATG7) renders hepatocytes vulnerable to ER stress and insulin resistance, and conversely restoration of hepatic autophagy be means of ATG7 overexpression can improve insulin sensitivity." (PMID 25653476, 2015). "Tissue-specific overexpression of Atg7 in liver tissue is sufficient to ameliorate autophagic impairments resulting from suppressed Atg7 expression, such as endoplasmic reticulum stress and insulin resistance." (PMID 40354374, 2025). "Moreover, CaMKIV inhibited activated ER stress and insulin resistance in Atg7 siRNA transfected adipocytes." (PMID 32660483, 2020). "Moreover ATG7 knockout mice models have displayed severe morphological abnormalities in the structure of white adipocytes, as well as an aggravated insulin resistance with increased lipid content and inflammatory changes." (PMID 30908504, 2019). "The reduced expression of Atg7 in the liver induced by adenovirus-mediated delivery of shAtg7 leads to increased endoplasmic reticulum stress and worsened insulin resistance in lean mice, whereas the adenovirus-mediated overexpression of WT Atg7 relieves these features in obese mice." (PMID 29540751, 2018).